TGFB1 (transforming growth factor beta 1)
Diseases named in the same sentence as TGFB1 in open-access papers (continued):
Sharing a sentence is not in itself a finding about the gene and the disease.
melanoma (continued). "Finally, we observed a significant negative Spearman correlation (r = −0.4021; p = 0.0376) between the two Down-miRs (i.e. miR-204-5p and miR-199b-5p) and the four Up-genes (i.e. VEGFA, TGFβ1, CCL5 and CXCL2) only in melanoma biopsies progressed after targeted therapies (PD samples)." (PMID 36418472, 2023). "However, we did not observe any significant changes in TGFβ1 or beta-catenin protein levels in either HAT1-knockdown or HAT1-KO melanoma cells." (PMID 32371878, 2020). "Given that somatic mutations are positively associated with both overall survival and response to checkpoint blockade in melanoma, we also asked whether TGFB1 expression predicted for overall survival independent of mutation." (PMID 28448494, 2017). "HO-1 is known to promote cell proliferation in melanoma through the B-Raf-ERK signaling pathway, thus suggesting that the CoPP-induced HO-1 could have also promoted ARPE-19 cell proliferation through the activation of the same signaling pathway, which led to the overexpression of Ki-67 and TGFβ1." (PMID 39857426, 2025). "Malignant melanoma was the only tumor type where TGFB1 expression significantly correlated with all four variables and overall survival, suggesting that the integrin β1 / TGF-β1 / host response phenotype we identified might be uniquely associated with anti-melanoma activity." (PMID 28448494, 2017). "For example, in melanoma, CCR5 was found to induce EMT through the secretion of TGFβ1 by CCR5+ cancer cells, triggering non-canonical TGFβ-mediated activation of the PI3K/Akt/GSK3β signaling pathway." (PMID 39409924, 2024). "Likewise, TGFβ1 did not alter pERK levels in MEKi-treated melanoma cells, while there was a slight increase in pERK levels upon TGFβ1 stimulation in some of the cell lines, consistent with previous findings that TGFβ can activate the MAPK pathway in a context-dependent manner." (PMID 39709491, 2024). "They did not report TGFB1 and its receptors as direct downstream targets of PHF8, as we find in melanoma." (PMID 35179962, 2022). "Despite a noticeable increase in TGFβ1 expression after progression into the negative SLN, no further enhancement was observed with melanoma metastasis to the lymph nodes." (PMID 17565341, 2007).
diabetes (644 papers, 2000 to 2026). "Diabetes increased kidney expression of genes associated with injury (Kim1, ten-fold), senescence (Cdkn1a, Cdkn2a, 10 to 18-fold) and fibrosis (Tgfb1, Ctgf, Pai1, Timp1, Col1α1, Col4α1 and Fn1, two- to six-fold)." (PMID 41332229, 2025). "GPX3 (glutathione peroxidase 3) and TGF-β1 (transforming growth factor-beta 1) were selected as biomarkers related to oxidative stress regulation and inflammation, both of which are closely linked to metabolic dysfunction and diabetes progression." (PMID 40299518, 2025). "For example, TGFβ1 was associated with adipose tissue fibrosis, which is characterized by collagen accumulation and M1 macrophage polarization, and diabetes was associated with AGEs." (PMID 39120271, 2024). "Collectively, these findings suggest that TGFβ1 is overexpressed in renal tubulointerstitia in DN as opposed to healthy living controls, associated with accelerated kidney aging in diabetes." (PMID 37758806, 2023). "In diabetes, hyperglycaemia causes up-regulation of endothelin 1 (ET-1) and transforming growth factor beta 1 (TGF-β1)." (PMID 25753689, 2015). "The TGFB1 gene rs1800469 polymorphism was associated with myocardial infarction in men, independently from the potentially confounding factors: age, arterial hypertension, hypercholesterolemia, cigarette smoking and diabetes mellitus." (PMID 36672663, 2023). "In the present study, we have decided to evaluate if serum transforming growth factor-beta 1 (TGF-β1) concentrations may have diagnostic value in predicting the occurrence of diabetic retinopathy (DR) in juvenile patients with type 1 diabetes mellitus (T1DM)." (PMID 23671881, 2013). "Additionally, our analysis highlighted the enhanced expression of certain inflammatory markers (e.g., CCL2 and TGFB1/2) during ED with diabetes mellitus, suggesting a pivotal role of local inflammatory responses in the early pathophysiology of diabetes-associated ED." (PMID 39766863, 2024). "Therefore, we speculate that SPARC at the onset of diabetes may be associated with regulation of Tgfb1 as well as Tgfb1-mediated TNFα production." (PMID 26110898, 2015). "Among the key molecular mediators in diabetes pathology, transforming growth factor-beta 1 (TGF-β1) plays a critical role in tissue remodeling, fibrosis, and chronic inflammation." (PMID 40299518, 2025). "In considering potential mechanisms for transcript downregulation, we perfomed qRT-PCR for Tgfb1, Tnfa and Ccn2, three genes well-established for their roles in the development of diabetes complications." (PMID 39582036, 2024). "Supportive evidence from literature indicates the protective effect of TGFB1 on diabetes development." (PMID 39464889, 2024). "In hyperglycemia-induced mice, Dap reduced the expression of TGFβ1, fibronectin, and COL IV to decrease the progression of diabetes-associated glomerulosclerosis." (PMID 38282657, 2024). "Under endocrine disorder ‘experimentally induced diabetes’ was linked to Harvey Rat Sarcoma Viral Oncogene Homolog (H-RAS), C-X-C motif chemokine receptor 4 (CXCR4) and transforming growth factor-beta 1 (TGF-β1)." (PMID 36934129, 2023). "The usage of curcumin has been extended to protect against diabetes by inhibiting the endothelial nitric oxide synthase and transforming growth factor beta 1 (TGF-β1) in the kidney of rats through inhibiting p300/CBP and, thus, the repression of NF-κB." (PMID 36900446, 2023). "In this review, we explored interplay role of several factors including microRNAs which acts as a potential regulator of cardiac fibrosis connected with TGFβ-1 in diabetes mellitus." (PMID 37306727, 2023). "Overall, PTβR2I appeared to inhibit the TGFβ1/p-Smad2/3 pathway under normal glucose conditions while having no substantial inhibition effect when the glucose level was as high as that found in diabetes." (PMID 37422462, 2023).
diabetes (continued). "In an attempt to identify which cell types express TGFB1 and downregulate its expression in diabetes, we carried out in situ hybridization (ISH) in the bone tissues of mice." (PMID 36307522, 2022). "All types of resident renal cells and infiltrating inflammatory cells can act as sources and exacerbate the release of TGFβ1 in the pre-diabetes phase." (PMID 36430743, 2022). "Similar protective effects against β cell autoimmune injury and diabetes were also observed in NOD mice with α cell-specific Tgfb1 overexpression." (PMID 35327565, 2022). "Studies have shown that TGFβ1 levels are sensitive to high glucose levels in humans, in animals, and in vitro and that different pharmacological interventions used in the treatment of diabetes reduce TGFβ1 total serum levels." (PMID 35740425, 2022). "Fibrotic genes in the glomeruli were elevated by diabetes, including fibronectin (Fn1), TGFβ1 (Tgfb1), and collagen α-1 (IV) chain (Col4a), with significant attenuation in diabetic PPKM2Tg mice." (PMID 35133981, 2022). "FoxO1 is a TGFβ-1 downstream crucial player in cardiac fibroblast conversion into cardiac myofibroblasts, which, under pathological conditions such as diabetes mellitus, synthesizes and secretes high amounts of ECM proteins." (PMID 34803741, 2021). "In parallel, this GapmeR also ameliorated diabetes-induced expression of profibrotic genes Tgfβ1, Col1a2, Col4a1, and Ctgf in renal glomeruli and reduced key features of early DN in mice." (PMID 34234740, 2021). "Cone communicates with microglia through secreted TGFβ2 instead of TGFβ1, suggesting a novel target sites of TGFβ mediating the effects of microglia under diabetes mellitus." (PMID 34434927, 2021). "Sex hormones are reported to influence TGFβ1, while in diabetes mellitus sex differences were found to be related to onset and duration of diabetes, glycemic control, puberty and menopause." (PMID 33334029, 2020). "A Multivariate ANOVA analysis (M-ANOVA) was also carried out to assess the effects of fixed factors on glycated hemoglobin (HbA1c) levels, TGFβ1, and diabetes duration." (PMID 33334029, 2020). "The equality of the covariance matrix of dependent variables was satisfied, and the effects of independent variables (group, insulin treatment, glycemic control, gender) on HbA1c, TGFβ1 and the duration of diabetes were analyzed." (PMID 33334029, 2020). "It meant that overexpression of DCN attenuated diabetes-induced myocardial fibrosis by inhibition of TGFβ1 pathway." (PMID 33365011, 2020). "Based on this assumption, we carried out a multivariate ANOVA analysis (M-ANOVA), which showed that the diagnosis group, glycemic control and gender (independent variables) influenced TGFβ1, HbA1c and duration of diabetes (dependent variables)." (PMID 33334029, 2020). "It was found that diabetes promoted the expression of both Collagen I and TGFβ1 levels, as compared to the Control group." (PMID 30450046, 2018). "A pivotal cytokine in the profibrotic responses, transforming growth factor beta 1 (Tgfβ1), was significantly increased in both diabetic groups (the effect of diabetes, P < 0.05 by two-way ANOVA)." (PMID 28774305, 2017). "In kidneys, AcSDKP also restored the diabetes-suppressed FGFR1 and P-MAP4K4 levels and the diabetes-induced TGFβ1 and TGFβ2 expression." (PMID 28771231, 2017). "In a subsequent study, treatment with the anti-TGFβ1 neutralization antibody (1D11) was shown to protect mice from obesity and diabetes." (PMID 28123053, 2017). "Meanwhile, TGFβ1 levels was decreased by zingerone (p<0.05), showing the potential of this compound in ameliorating diabetes-related fibrosis signalling activation." (PMID 29206854, 2017). "Several diabetes-related or inflammation-related genes are included in the TG-associated pathways, such as SMAD3, TGFB1, CDKN2B, and IL10." (PMID 26308950, 2015).
diabetes (continued). "Hyperglycemia in diabetes stimulates the increase in TGFβ-1 expression and, in turn, induces kidney multi-cellular hypertrophy through autocrine and paracrine pathways." (PMID 25849026, 2015). "All fibrogenic markers (transforming growth factor beta 1 levels, collagen deposition, fibrous capsule thickness, and foreign body giant cells) decreased after diabetes, whereas apoptosis (TUNEL) increased." (PMID 25372281, 2014). "Recently, we have shown that TGFβ1 mediates vasoreparative dysfunction in CD34+cells from diabetics and that the transient blockade of the expression of TGFβ1 or PAI-1, the main gene target of TGFβ, restores vasoreparative function." (PMID 24713821, 2014). "On the other hand, blockage of TGFβ1 prevented renal especially glomerular hypertrophy and fibrosis in mouse with diabetes." (PMID 22879939, 2012). "Protein and mRNA levels of TGFβ1 are significantly increased in the renal glomeruli and tubulointerstitium of animal models of diabetes and in humans with diabetes." (PMID 17319955, 2007). "In another study of high-fat diet-induced diabetes in mice, pterostilbene, a resveratrol analog, reduced the expression of TGFβ1, pSMAD3, SREBP1, and FAS, reduced ectopic lipid deposition, alleviated renal tubular injury and fibrosis, and improved renal function." (PMID 41020857, 2025). "TGFβ1 is reduced in the wound fluid of diabetic patients compared to non-diabetic patients, which could add to delayed wound healing in diabetes." (PMID 38986808, 2025). "Overexpression of TGFB1 under a rat insulin promoter reduces the risk of diabetes in T1D susceptible nonobese diabetic mice." (PMID 39464889, 2024). "Additionally, higher TGFβ-1 levels were found to correlate with HbA1c levels, the duration of diabetes, and the progression of DR." (PMID 38474297, 2024). "The idea was based on the high quantity of transforming growth factor β 1 (TGFB1) and mimecan in AT EVs of subjects with obesity, as well as elevated levels of TGFB1- and mimecan-containing EVs in the plasma of subjects with obesity and diabetes." (PMID 38965596, 2024). "In addition, insulin resistance combined with hyperinsulinemia and hyperglycemia has been reported to upregulate the expression of TGFβ1 in the kidneys in the pre-diabetes phase in humans." (PMID 36430743, 2022). "Likewise, TGFβ1 levels are elevated systemically and in aqueous humor in patients with diabetes and diabetic retinopathy." (PMID 35740425, 2022). "In addition to the TGFβ1-phospho-Smad2/3 pathway involved in vascular remodeling, we also detected MMPs expression and activity in diabetes and HG-treated VSMC." (PMID 34712140, 2021). "Furthermore, we carried out a Multivariate ANOVA in order to unveil the effects of fixed factors (independent variables) on dependent variables (diabetes duration, glycated hemoglobin HbA1c, TGFβ1, VEGFA, PlGF)." (PMID 33334029, 2020). "The proinflammatory cytokine profiles in the diabetes mellitus patients, including IL-8, were correlated with severity of the course of disease and polymorphisms of pro-inflammatory cytokine genes (CCL2, TGFB1, IL8, CCR5, and MMP9) were found to be associated with the risk of diabetic nephropathy." (PMID 24386171, 2013). "It has been reported that Nox4 is the major source of ROS in the kidneys during the early stages of diabetes mellitus and Nox4-derived ROS are considered to mediate renal hypertrophy, increase fibronectin expression and myofibroblast activation induced by TGFβ1." (PMID 23991195, 2013). "In addition, post-treatment with NaB dramatically reduces histological changes such as the collagen deposition and fibrosis, while also diminishing the expression levels of α-SMA, iNOS, eNOS, fibronectin, collagen I, NFκB, TGFβ1, DNA damage and apoptosis in the diabetic kidney." (PMID 38616256, 2024). "In addition to high ambient glucose and TGFβ1 used in the present study, other mediators are also involved in DKD and may contribute to diabetes-associated cellular senescence in the kidney." (PMID 37758806, 2023).
diabetes (continued). "However, it is unknown whether TGFβ1 mediates diabetes-induced premature senescence of renal parenchymal cells." (PMID 37758806, 2023). "Therefore, a variety of approaches have been adopted to restore functions of EPC in patients with diabetes, including inhibition of TGFβ1, treatment with peroxisome proliferator-activated receptor γ and δ, improvement of EPC mobilization with stromal cell-derived factor-1." (PMID 33931128, 2021). "Finally, TGFβ1 levels correlated with HbA1c levels and duration of diabetes." (PMID 33334029, 2020). "Thus, significantly reduced Tgfβ1 gene expression in LiasHigh/HighIns2Akita mice may play a role in attenuation of the adverse effect of diabetes mellitus on kidney structure and function." (PMID 27706190, 2016). "A renoprotective effect has also been reported where the activation of adenosine monophosphate-activated protein kinase (AMPK) by cocoa enriched polyphenols followed by reduction in NOX4/TGFβ-1 signaling may have a therapeutic potential in diabetic nephropathy in experimental diabetes mellitus." (PMID 27599802, 2016). "The analysis of individual studies on miR-146 in the context of diabetes yielded a heatmap that showcased the prevalence of several genes, namely IRAK1, TRAF6, IL-6, TNF-α, NUMB, EGFR, and TGFβ-1, among others." (PMID 37560309, 2023). "In this study, through bioinformatics analysis, we screened seven DCRGs, including PPARG, MMP9, CTNNB1, TNF, TGFB1, PTGS2, and HIF1A, and established a DCIN to comprehensively understand the diabetes-inflammation-cancer interaction." (PMID 37033970, 2023). "Significantly less TGFβ1 was detected in GFP+ microglia from mice with IL-10 depletion, suggesting that IL-10 depletion suppressed the M2c differentiation of microglia in diabetes." (PMID 35935990, 2022). "TGFB1 release from SAT is increased in obesity while systemic blockade of its signaling protects mice from obesity, diabetes and hepatic steatosis." (PMID 34638880, 2021). "In diabetes, AGEs can induce the production of chemokines such as MCP-1, profibrotic cytokines, and growth factors including TGFβ1 and connective tissue growth factor (CTGF), and the angiogenic growth factor VEGF." (PMID 32210089, 2020). "In contrast, the expression of the AGE receptor (RAGE) and the transforming growth factor β1 (TGFβ1) in the kidney cortex was upregulated due to STZ treatment and diabetes mellitus." (PMID 24023581, 2013). "Similarly, the three-way ANOVA showed that diabetes mellitus (p<0.05) and CD64 KO (p<0.01) significantly influenced the TGFβ1 production." (PMID 38524127, 2024). "By week 12 of diabetes, we identified a 2- to 3-fold increase in the kidney gene expression of Tgfb1, but found no increase in Ctgf/Ccn2 or Pdgfb mRNA levels." (PMID 38391050, 2024). "We tested with a M-ANOVA the effects of all independent variables only on the duration of diabetes, HbA1 and TGFβ1, because these dependent variables were normally distributed and correlated significantly." (PMID 33334029, 2020). "In mice treated with empagliflozin, the diabetes-induced upregulation of Tgfβ1 and Cd14 was absent and there was a trend for reduced Fn1 expression compared to vehicle-treated db/db mice (P = 0.059)." (PMID 27226136, 2016). "Treatment of nonobese diabetic mice with the DPP-4 inhibitor, NVP-DPP728 (30 mg/kg), significantly increased the levels of plasma transforming growth factor beta-1 (TGF-β1), an anti-inflammatory cytokine, and increased CD4+CD25+FoxP3+ regulatory T cells, contributing to the remission of diabetes." (PMID 27110066, 2016). "Metformin did not restore the diabetes-induced upregulation of any genes but tended to decrease Fn1 (P = 0.095) and Tgfβ1 (P = 0.068) compared to db/db vehicle." (PMID 27226136, 2016). "In diabetes, activated nuclear factor-κB (NF-κB) translocates into the nucleus and triggers the expression of its target genes, including intercellular adhesion molecule-1 (ICAM-1) and transforming growth factor-beta 1 (TGF-β1)." (PMID 23718910, 2013).
diabetes (continued). "The cytokine IL-11, expressed in response to TGFβ1/SMAD activation, seems to play a pivotal role in the transition from adaptive repair processes to maladaptive damaging processes in CKD in response to kidney insult, whether it stems from AKI or a chronic disease such as diabetes." (PMID 38732588, 2024).